DSC2 (desmocollin 2)
Diseases named in the same sentence as DSC2 in open-access papers (continued):
Sharing a sentence is not in itself a finding about the gene and the disease.
esophageal squamous cell carcinoma (5 papers, 2014 to 2024). Esophageal squamous cell carcinoma (ESCC) is a type of esophageal carcinoma (EC) that can affect any part of the esophagus, but is usually located in the upper or middle third. "In contrast, a reduction in DSC2 expression has been identified in other cancer types such as colorectal, lung and esophageal squamous cell carcinoma." (PMID 35387118, 2022). "In the esophageal squamous cell carcinoma, DSC2 displayed a role in tumour differentiation, metastasis and patients’ clinical outcomes." (PMID 32299152, 2020). "The tumor metastasis suppressing property of DSC2 in esophageal squamous cell carcinoma (ESCC) has been described, however, its contribution to cell cohesion in ESCC remains to be elucidated." (PMID 25119898, 2014). "Similarly, decreased expression of Dsc2 promoted tumorigenic behavior in colorectal carcinoma, pancreatic ductal carcinoma and esophageal squamous cell carcinoma." (PMID 38671389, 2024). "Furthermore, aberrant expression of DSC2 had been reported in a pancreatic ductal adenocarcinoma, oral squamous carcinoma and esophageal squamous cell carcinoma." (PMID 37421607, 2023). "In addition, the level of DSC2 was reported to be negatively correlated with lymph node metastasis and pTNM stages in esophageal squamous cell carcinoma." (PMID 37421607, 2023). "In human esophageal squamous cell carcinoma (ESCC), the expression of DSC2 has only recently been described." (PMID 25119898, 2014).
lung carcinoma (5 papers, 2021 to 2025). "Higher expression is linked with some cancers (AHRR, DSC2), poorer prognosis of lung cancer (P2RY6), and cardiovascular diseases (GPR15, DCS2)." (PMID 40579423, 2025). "Recent studies have found that increased expression of DSC2 in lung cancer is associated with lower overall survival and poor prognosis of patients." (PMID 37779876, 2023). "And, in a more recent study, breast and lung cancer cells resistant to shear stress revealed an up-regulation of DSC2 and PKP1, leading to more CTC cluster formation and enhanced cell survival in circulation via activation of the PI3K/AKT/Bcl-2 pathway." (PMID 36927383, 2023). "Furthermore, higher expression of DSC2 and PKP1 was correlated with lower overall survival and worse disease progression in patients with breast and lung cancer." (PMID 36927383, 2023). "Additionally, LAMC2 promotes the chemotactic function of granulocytes; DSC2 correlates positively with adhesion, migration, and infiltration of granulocytes; and KRT6A protein inhibits the proliferation, migration and invasion abilities of lung cancer cells." (PMID 36817446, 2023).
psoriasis (5 papers, 2016 to 2026). An autoimmune condition characterized by red, well-delineated plaques with silvery scales that are usually on the extensor surfaces and scalp. "Spatial transcriptomics (STs) revealed that luteolin preferentially targets DC-enriched spatial domains and restores desmosomal protein expression (e.g., DSC2), which is dysregulated in psoriasis." (PMID 41814938, 2026). "In the psoriasis lesional skin, high expression of desmocollin 2 (DSC2) and desmoglein 3 (DSG3) was also observed, in contrast to the low expression of desmocollin 1 (DSC1) and desmoglein 1 (DSG1)." (PMID 36841845, 2023).
gastric cancer (4 papers, 2023). A primary or metastatic malignant neoplasm involving the stomach. "DSC2 also inhibited the metastasis of gastric cancer by inhibiting the BRD4/Snail signaling pathway and the transcriptional activity of β-catenin." (PMID 36817446, 2023). "DSC2 also was reported to inhibit the migration and invasion ability of gastric cancer, lung cancer, squamous cell carcinoma of head and neck, and so on." (PMID 37421607, 2023). "Additionally, miR-205-5p targets a plethora of communication factors, including, e.g., VEGF and FGF1 leading to reduced angiogenesis in gastric cancer, whereas exosomal miR-205-5p induces angiogenesis in nasopharyngeal carcinoma by targeting desmocollin-2." (PMID 38003618, 2023).
Arrhythmia (3 papers, 2018 to 2024). Any cardiac rhythm other than the normal sinus rhythm. "Compared to the MAF (< 0.01%) of inherited arrhythmia and CMs in the population, the MAF of DSC2 p.I520T (0.02%) is relatively high." (PMID 34819141, 2021).
bladder cancer (3 papers, 2005 to 2025). "Research have released that DSC2 was associated with immune cell infiltration in bladder cancer." (PMID 37779876, 2023). "We examined the constitutive expression levels of desmocollin-2 and desmoglein-2 in the panel of bladder carcinoma cell lines." (PMID 15942628, 2005).
heart failure (3 papers, 2021 to 2023). Inability of the heart to pump blood at an adequate rate to meet tissue metabolic requirements. "In the present study, PKP2, DSG2, and DSC2-KOs experiment with a decrease in ATPase expression (codified for SERCA), indicating that the absence of those genes may be linked to heart failure, a clinical feature present in ACM phenotype." (PMID 36768439, 2023).
melanoma (3 papers, 2016 to 2024). A malignant, usually aggressive tumor composed of atypical, neoplastic melanocytes. "The results indicate that in trunk subtype melanomas, the protein expression levels of DSC2, DSC3, DSG1, KRT6B, PKP1, and PKP3 are significantly higher than those in adjacent normal samples, suggesting the crucial roles of these central genes in SKCM progression." (PMID 38660305, 2024). "Immune infiltration analysis revealed a significant correlation between the expression levels of DSC2, DSC3, and the infiltration of various immune cells, highlighting the intricate relationship between the tumor microenvironment and melanoma progression." (PMID 38660305, 2024). "Our analysis, grounded in WGCNA and PPI networks, identified six genes (DSC2, DSC3, DSG1, KRT6B, PKP1, PKP3) with pivotal roles in melanoma’s oxidative stress response and immune infiltration." (PMID 38660305, 2024). "As the expression levels of DSC2, DSC3, DSG1, KRT6B, PKP1, and PKP3 increased, the overall survival time of trunk subtype melanoma patients significantly decreased." (PMID 38660305, 2024). "In contrast, expression of other desmosomal cadherins (DSG1, DSG3, DSC1, DSC2, DSC3) was negligible, revealing that DSG2 is unique within this gene family for its expression in a large proportion of melanoma cell lines." (PMID 27340778, 2016).
Palmoplantar keratoderma (3 papers, 2016 to 2023). Abnormal thickening of the skin of the palms of the hands and the soles of the feet. "Mutations in DSC2 cause palmoplantar keratoderma and woolly hair syndrome, characterized by thickened skin on the feet and hands and curly, brittle hair due to epidermal differentiation and cornification disorders." (PMID 37800682, 2023). "In addition to Naxos and Carvajal diseases, homozygous mutations of DSC2 cause ACM with mild palmoplantar keratoderma and woolly hair." (PMID 36008935, 2022).
pancreatic cancer (3 papers, 2020 to 2022). "Similarly, DSC2, DSG2, and LAMA3 were also found to be highly expressed and significantly associated with poor prognosis in pancreatic cancer." (PMID 35570408, 2022). "Seven GRGs: CDK1, DSC2, MET, PYGL, CHST12, ERO1A, and SLC35A3 were selected to construct the prognostic model related to the overall survival rate of patients with pancreatic cancer." (PMID 33912561, 2021). "Expression analysis further revealed that CDK1, DSC2, ERO1A, MET, PYGL, and SLC35A3 were highly expressed in pancreatic cancer while CHST12 was highly expressed in normal pancreatic tissues." (PMID 33912561, 2021). "CDK1, DSC2, ERO1A, MET, PYGL, and SLC35A3 were highly expressed while CHST12 was decreased in pancreatic cancer." (PMID 33912561, 2021).
Sepsis (3 papers, 2022 to 2025). Sepsis is defined as life-threatening organ dysfunction caused by a dysregulated host response to infection. "In our exploration, we identify a clear linkage between key glycolytic genes, IER3 and DSC2, and the behavior of neutrophils during sepsis." (PMID 39331858, 2024). "Harnessing the expression profiles of pivotal glycolytic genes: PPARG, DSC2, and IER3: we’ve devised a predictive model that seeks to revolutionize the diagnostic approach to sepsis." (PMID 39331858, 2024). "In line with our endeavor to “unveil the glycolysis in sepsis,” the discovery of IER3, DSC2, and PPARG reinforces their cardinal roles in sepsis pathogenesis." (PMID 39331858, 2024). "Among the myriad genes, IER3, DSC2, and PPARG emerged as linchpins, their prominence in sepsis further validated through ROC analytics." (PMID 39331858, 2024). "In conclusion, our exploration underscores the pivotal role of glycolysis in sepsis, emphasizing the significance of IER3, DSC2, and PPARG." (PMID 39331858, 2024). "However, in our study, there were specific proteins only showing changes in pigs with meningitis but not in pigs with sepsis due to LPS administration, like VCL, DSC2 or HBB." (PMID 36430174, 2022).
Arrhythmogenic right ventricular dysplasia 11 (2 papers, 2016 to 2021). "DSC2, mapping to chromosome 18, is the gene for arrhythmogenic right ventricular dysplasia 11 (OMIM #610476)." (PMID 26788539, 2016).
Carvajal syndrome (2 papers, 2008 to 2025). "Both conditions are inherited in an autosomal recessive manner, with Naxos disease caused by DSG2 mutations and Carvajal syndrome caused by DSC2 mutations." (PMID 41426600, 2025).
diabetes (2 papers, 2022 to 2024). "Whether diabetes is a coincidental finding in this patient or a possible feature of complete DSC2 deficiency remains to be established." (PMID 35159392, 2022). "Although pancreatic disorders or diabetes are not recognized characteristic features of patients with DSC2 mutations, a case of nonautoimmune diabetes diagnosed as type 2 diabetes was reported in one of the few described patients with biallelic DSC2 deficiency." (PMID 35159392, 2022).
esophageal cancer (2 papers, 2014 to 2021). A primary or metastatic malignant neoplasm involving the esophagus. "Therefore, in esophageal carcinoma cells, DSC2 may affect cytoskeleton rearrangement via alternative signaling pathways, which requires extensive investigation to determine." (PMID 25119898, 2014).
familial hypercholesterolemia (2 papers, 2020 to 2025). An inheritable form of hyperlipidemia, in which there are excess lipids in the blood.
lung adenocarcinoma (2 papers, 2020 to 2023). A carcinoma that arises from the lung and is characterized by the presence of malignant glandular epithelial cells. "On the other hand, based on the TCGA Pan-Cancer dataset, DSC2 was upregulated in most cancers including lung adenocarcinoma, breast invasive carcinoma, and so on." (PMID 37779876, 2023). "Based on GEPIA database, seven of the top ten co-expressed genes were highly expressed in lung adenocarcinoma (DSC2, SLC2A1, ARNTL2, ERO1L, ECT2, ANLN and LAMC2)." (PMID 32095325, 2020).
Marfan syndrome (2 papers, 2014 to 2021). A disorder of the connective tissue. "Three new variants, including 1 deletion in DSC2, 1 missense SNPs in LRP1, and 1 nonsense SNP in FBN1 were confirmed to exist only in Marfan syndrome patients." (PMID 24484584, 2014).
pancreatic ductal adenocarcinoma (2 papers, 2024 to 2025). An infiltrating adenocarcinoma that arises from the epithelial cells of the pancreas. "DSC2 has been well characterised in pancreatic ductal adenocarcinoma (PDAC); therefore, we focused this study on DSG2 in PCSCs." (PMID 40615400, 2025). "We employed the pancreatic ductal adenocarcinoma cell line AsPC-1 bearing a KO of DSG2 and generated hepatocyte-specific Dsg2 and Dsc2 KO mouse models." (PMID 39107343, 2024). "We applied the pancreatic ductal adenocarcinoma cell line AsPC-1 with and without a knockout (KO) of DSG2 and generated mouse lines with a hepatocyte-specific KO of the known interacting partners of DSG2 (DSG2 and desmocollin-2)." (PMID 39107343, 2024).
prostate carcinoma (2 papers, 2014 to 2025). A carcinoma that arises from epithelial cells of the prostate gland. "Inhibition of DSC2 promotes proliferation, colony formation, migration, and invasion of LNCaP cells and PC-3 cells, and inhibits apoptosis of LNCaP cells and PC-3 cells, which provides a basis for the treatment of prostate cancer." (PMID 39790460, 2025). "We then selected six genes (HNRNPH1, DSC2, FBXO9, MANEA, OR51E1, PRR15L) for validation by qRT-PCR that were over-expressed in prostate cancer across all datasets and showed high fold changes in our microarray." (PMID 25003216, 2014).
Right ventricular cardiomyopathy (2 papers, 2020 to 2024). Right ventricular dysfunction (global or regional) with functional and morphological right ventricular abnormalities, with or without left ventricular disease. "In another study, the genome of one supercentenarian had a pathogenic mutation in DSC2, known to predispose to arrhythmogenic right ventricular cardiomyopathy, which is a potentially fatal condition, causing affected individuals to die of sudden cardiac death." (PMID 38653581, 2024).
triple-negative breast carcinoma (2 papers, 2023). An invasive breast carcinoma which is negative for expression of estrogen receptor (ER), progesterone receptor (PR), and human epidermal growth factor receptor 2 (HER2). "In addition, DSC2 is up-regulated in triple negative breast cancer and is associated with early lymph node metastasis." (PMID 37779876, 2023). "Functional consequences of DSC2 overexpression and DSC2 knock down were investigated in the triple negative breast cancer (TNBC) cell line MDA-MB-231 and its brain-seeking subline MDA-MB-231-BR, respectively in vitro and in vivo." (PMID 36927383, 2023).
Ventricular arrhythmia (2 papers, 2018 to 2022). "Patients are predisposed to a wide spectrum of clinical presentations, such as ventricular arrhythmia and SCD, which are associated with mutations in desmosome genes, such as plakoglobin (JUP), desmoplakin (DSP), plakophilin 2 (PKP2), desmoglein 2 (DSG2), and desmocollin 2 (DSC2)." (PMID 35433691, 2022).
Autoimmunity (1 paper, 2023). The occurrence of an immune reaction against the organism's own cells or tissues. "Furthermore, the autoimmunity exhibited by lines expressing CG-1 domain mutants could also be due to the monitoring of the transcriptional activity of CAMTA3 either by DSC1/DSC2 or other NLRs, or the CAMTA3-NLRs complex may modulate the CAMTA3 transcriptional activity." (PMID 37566065, 2023).
Becker muscular dystrophy (1 paper, 2024). Becker muscular dystrophy (BMD) is a neuromuscular disease characterized by progressive muscle wasting and weakness due to degeneration of skeletal, smooth and cardiac muscle. "At age 13, he was diagnosed Becker muscular dystrophy carrying with the causative mutation in gene DMD (chrX:32,841,413–32,862,977, Hemizygous mutation), and gene testing showed the comorbid mutations of ABCB4(chr7:87041219, heterozygous mutation) and DSC2(chr18:28659938, heterozygous mutation)." (PMID 39044225, 2024).
Bradycardia (1 paper, 2022). A slower than normal heart rate (in adults, slower than 60 beats per minute). "Low levels of DSC2 expression could lead to bradycardia, ventricular dilatation, abnormal cardiac contractility, and cardiomyocyte edema." (PMID 36367775, 2022).
cardiac hypertrophy (1 paper, 2020). "As a main result we found that AGAT−/− mice exhibited altered gene expression related to energy metabolism (Fbp2, Ucp2), cardiac hypertrophy and fibrosis (Nppa, Ctgf), immune response (Fgl2), and the conduction system of the heart (Dsc2, Ehd4, Hcn2, Hcn4, Scn4a, Scn4b)." (PMID 32179820, 2020).
chronic lymphocytic leukemia (1 paper, 2021). "Mucosal involvement occurred in two patients, one with chronic lymphocytic leukemia with an overlap IEND-PNP and another with PVeg features.‡ In both cases anti-Dsc2 was detected." (PMID 34567003, 2021).
colonic adenocarcinoma (1 paper, 2023). "Upon knockdown of DSG2, DSC2 has been shown to be upregulated in colonic adenocarcinoma cell lines, and this might explain why we can still observe a positive adhesiotropic effect of EGFR or SRC inhibition upon Dsg2 knockdown." (PMID 36795511, 2023).
colorectal adenocarcinoma (1 paper, 2006). The most common type of colorectal carcinoma. "We have found switching between desmocollins in sporadic colorectal adenocarcinoma with a reduction in Dsc2 protein (in 8/16 samples analysed by immunohistochemistry) being accompanied by de novo expression of Dsc1 (16/16) and Dsc3 (7/16)." (PMID 17088906, 2006).
colorectal polyposis (1 paper, 2025). "While predisposing variants in genes such as NTHL1, MSH3, POLE, POLD1, DSC2, and PIEZO1 have been associated with colorectal polyposis, they do not fully mimic the classical FAP phenotype." (PMID 41204315, 2025).
congenital heart disease (1 paper, 2022). A heart disease that is present at birth. "Patients with biallelic DSC2 mutations may present additional clinical features to heart defects, including skin and hair abnormalities." (PMID 35159392, 2022).
Harlequin ichthyosis (1 paper, 2022). Harlequin ichthyosis (HI) is the most severe variant of autosomal recessive congenital ichthyosis (ARCI; see this term). "Interestingly, some of these genes, i.e. KRT1, KRT9, KRT16, DSG1, DSC2 and JUP, are mutated in hereditary PPKs, while the ABCA12 gene is defective in harlequin ichthyosis characterized by the loss of the skin lipid barrier." (PMID 35854363, 2022).
head and neck cancer (1 paper, 2021). A primary or metastatic malignant neoplasm affecting the head and neck. "Based on the literature review, DMBA-induced malignant transformation of oral mucosa epithelium reduced the number of desmosomes, and the Desmocollin-2 expression level was reduced in head and neck cancer tissues with poor clinical outcomes." (PMID 35054231, 2021).
liver cancer (1 paper, 2022). An epithelial or non-epithelial malignant neoplasm that arises from the liver. "In a conclusion, DSC2 was a tumor suppressor with low expression in liver cancer." (PMID 36367775, 2022).
metastasis (1 paper, 2024). The spread or migration of cancer cells from one part of the body (where they first appeared) to another. "Moreover, the use of DSC2 expression as a predictive marker for the development of brain and lung metastasis is interesting." (PMID 38539508, 2024).
osteosarcoma (1 paper, 2023). A usually aggressive malignant bone-forming mesenchymal neoplasm, predominantly affecting adolescents and young adults. "As DSC2 is closely associated with osteosarcoma, we were concerned about the immune landscape associated with DSC2." (PMID 37779876, 2023).
ovarian carcinoma (1 paper, 2016). A malignant neoplasm originating from the surface ovarian epithelium. "Their encoded proteins, E-cadherin, desmocollin 2 and junctional adhesion molecule-A (JAM-A) had been widely accepted as prognostic biomarkers for multiple epithelial cancers, including ovarian cancer." (PMID 27835595, 2016).
renal carcinoma (1 paper, 2018). A carcinoma arising from the epithelium of the renal parenchyma or the renal pelvis. "From the unique set of genes detected by knnAUC, four genes, APOE, DSC2, SEC63 and SYCP1 were reported to be relevant to renal cancer." (PMID 30466390, 2018).
renal cell carcinoma (1 paper, 2018). "DSC2 is associated with development and progression of renal cell carcinoma (RCC)." (PMID 30466390, 2018).
venous ulcers (1 paper, 2022). "DSC2 is a desmosomal cadherin that mediates in mammalian and fish tissue development processes involving cell-cell adhesion and has been found up-regulated in human venous ulcers." (PMID 35401509, 2022).